MIR6758 (microRNA 6758)
Synonyms: hsa-mir-6758
Gene: MicroRNA gene on chromosome 12 (57,512,688 to 57,512,750, forward strand). Ensembl gene ENSG00000284152.
Homologues: Orthologues: chimpanzee MIR6758 (100% identical).